LY6S (lymphocyte antigen 6 family member S)
Synonyms: LY6A
Tractability: Antibody: UniProt places it where antibodies can reach, with medium confidence; UniProt predicts a signal peptide or a membrane-spanning region; its Gene Ontology location is reachable by antibodies, with medium confidence.
Gene: Protein-coding gene on chromosome 8 (143,040,839 to 143,048,357, reverse strand). Ensembl gene ENSG00000291309.
Subcellular location: Cell membrane
Gene Ontology:
Molecular function: acetylcholine receptor binding; acetylcholine receptor inhibitor activity
Biological process: acetylcholine receptor signaling pathway
Cellular component: plasma membrane; synapse
Homologues: Orthologues: rat Ly6c (44% identical), rat Ly6cl1 (44% identical), mouse Ly6f (43% identical), rat Ly6i (43% identical), rat Ly6al1 (42% identical), mouse Ly6g2 (41% identical), mouse Ly6a (40% identical), mouse Ly6c2 (40% identical), mouse Ly6g (40% identical), mouse Ly6i (38% identical), mouse Ly6c1 (32% identical). Paralogues in human: LY6H (35% identical), LY6L (29% identical).
Diseases named in the same sentence as LY6S in open-access papers:
LY6S is named in the same sentence as 36 diseases in open-access papers, as found by Europe PMC text mining. Sharing a sentence is not in itself a finding about the gene and the disease. The quoted sentences say what the papers report.
leukemia (3 papers, 2014 to 2025). A malignant (clonal) hematologic disorder, involving hematopoietic stem cells and characterized by the presence of primitive or atypical myeloid or lymphoid cells in the bone marrow and the blood. "The expression of LY6A/LY6S seems to be restricted to pituitary tumours and a subset of non-classical lymphoid cells of the spleen, and it could not be detected in hematopoietic cell lines or leukaemia patients." (PMID 39642167, 2025).
viral infections (1 paper, 2025). "Also, while Ly6a (SCA-1) is unique to mice, a recent study identified a human equivalent termed Ly6s, primarily expressed in splenic NCM and regulated by interferon signaling, that was linked to an inflammatory cell phenotype with resistance to viral infections." (PMID 39819562, 2025).
cancer (11 papers, 2014 to 2025). A tumor composed of atypical neoplastic, often pleomorphic cells that invade other tissues. "Besides LY6A/LY6S, other LY6 family members have been suggested as close homologues of the murine Ly6a gene, such as LY6D, LY6E, LY6H and LY6K, which were implicated as biomarkers for poor cancer prognosis and are frequently amplified in human cancer." (PMID 39642167, 2025).
LY6S also shares sentences with these, for which no sentence is quoted: tumor (22 papers); infection (9); atherosclerosis (4); breast carcinoma (4); colitis (4); pituitary tumor (3); adenoma (2); colonic tumors (2); diabetes (2); Helminth infections (2); lymphoma (2); melanoma (2); osteoporosis (2); ovarian carcinoma (2); prostate carcinoma (2); acute lymphoid leukemias (1); Cachexia (1); cavernomas (1); Chlamydia infection (1); chronic myelogenous leukemia (1); infectious disease (1); influenza infection (1); ischemic stroke (1); lung carcinoma (1); lymphoid leukemia (1); mesothelioma (1); metastasis (1); Myocardial fibrosis (1); osteosarcoma (1); osteosclerosis (1).
A further 3 diseases each share a sentence with LY6S in 1 paper.